BRAF (B-Raf proto-oncogene, serine/threonine kinase)
Diseases named in the same sentence as BRAF in open-access papers (continued):
Sharing a sentence is not in itself a finding about the gene and the disease.
melanoma (continued). "The discovery of somatic activating mutations in the BRAF gene in several cancers 5, including approximately 50% of melanomas 6, 7, provided the genetic foundation for the development of targeted treatment approaches for patients with BRAF‐mutant cancers." (PMID 28719152, 2017). "In the present study, we investigated the role of PTTG1 in melanoma cell proliferation, invasiveness and response to the BRAF inhibitor (BRAFi) dabrafenib by using two pairs of syngeneic melanoma cell lines sensitive or with acquired resistance to the drug." (PMID 29371923, 2017). "In melanoma cells, miR-524-5p directly interacts with the 3’-untranslated regions of both BRAF and ERK2 to inhibit MAPK/ERK signaling, cell proliferation, and cell migration." (PMID 29221202, 2017). "Previous studies have documented that PAK1 is amplified in BRAF wild type tumors and identified PAK inhibitors as agents that can slow the growth of melanoma xenografts and synergize with BRAF inhibitors to kill melanoma cells." (PMID 28753606, 2017). "All EPE-sensitive NRAS melanomas selected were resistant to the BRAF inhibitor vemurafenib, while the EPE peptide reduced their viability to 50%." (PMID 29180761, 2017). "Knockdown of BRAF directly downregulates EZH2 gene expression in melanoma cells and prostate cancer." (PMID 29202777, 2017). "We demonstrated that combination therapy was more efficacious than single agent alone in vitro and in vivo, whereas only in melanoma cell lines and PDX models concurrently containing BRAF V600E mutation and EZH2 gain." (PMID 29202777, 2017). "BRAF mutations were detected by HRM and Sanger in 54% (27/50) of the melanomas; the average allele frequency of those wt samples was 4.4% with an average variant coverage of 229.5 reads." (PMID 28356599, 2017). "On the contrary, the immune stimulation occurs during anti-BRAF treatment in consequence of the increased release of melanoma antigens that are highly captured by T-cells regulated by mature DCs." (PMID 29285320, 2017). "BCL2A1 has been recently described as an oncogene responsible for resistance to BRAF inhibition in melanoma." (PMID 28599664, 2017). "Taken together, these results identify PAK inhibitors as agents that can block the progression of early stage, BRAF mutant, RhoJ expressing melanomas by modulating BAD signaling." (PMID 28753606, 2017). "In BRAF mutant melanoma, BRAF inhibitor restores the compromised dendritic cells function, and, in particular, the production of IL-12 by dendritic cells." (PMID 28724377, 2017). "Since the approval of BRAF inhibitors for the treatment of metastatic melanoma, the importance of BRAF heterogeneity in melanoma samples has gained much attention." (PMID 28039443, 2017). "Multiple pathways that mediate resistance to BRAF inhibitors have been characterized in melanoma and colorectal carcinoma." (PMID 28350298, 2017). "Several of the genes that scored in these screens also scored in a previous vemurafenib resistance screen in BRAF-mutant melanoma." (PMID 28145866, 2017). "Unfortunately, resistance also develops to these combination therapies, for example, those that inhibit MAPK in BRAF mutant melanoma and CRC." (PMID 28431544, 2017). "In a mouse melanoma model, NF1 mutations cooperate with BRAF mutations in the pathogenesis of melanoma by preventing oncogene-induced senescence, an indication that NF1 plays a key role in early melanoma development." (PMID 28637487, 2017). "About 7% of all cancer cases carry a BRAF mutation, including 100% of hairy cell leukemia (HCL) cases, 50–60% of melanomas, 30–50% of papillary thyroid carcinomas, 10–20% of colorectal cancers, and 3–5% of non-small cell lung cancers." (PMID 28454577, 2017). "Based on the dominant role of the MAPK signalling pathway in therapy resistant BRAF-mutant melanoma cells, we were interested in a potential implication of its downstream effectors, the p90 ribosomal S6 kinases." (PMID 28415756, 2017).
melanoma (continued). "Light microscopy revealed stark changes in cell morphology following exposure to the Hsp90 and BRAF inhibitors, with the adoption of a dendritic appearance characteristic of melanoma cell re-differentiation." (PMID 28811486, 2017). "BRAF and MEK mutations contribute to dysfunction of the Ras-Raf-MEK-ERK Map kinase mutations that are present in greater than 90% of melanomas." (PMID 28331612, 2017). "About half of the melanomas harbor the mutation of BRAF gene (BRAFV600E, and possibly BRAFV600K), which results in constant activation of BRAF kinase." (PMID 28567163, 2017). "A major MAPK pathway related with murine melanoma is the ERK1/2 pathway associated with activation of the Ras/Raf/MEK/MAPK cascade, in which, mutations in oncogenes such as BRAF, culminate in exacerbated cell proliferation." (PMID 28079159, 2017). "BRAF inhibitors, including dabrafenib and vemurafenib, significantly improve survival in patients with metastatic BRAF mutant melanoma." (PMID 28993799, 2017). "Over the past five years, a new domain of personalized therapy has emerged for advanced melanoma patients with the introduction of BRAF and other MAP kinase pathway inhibitors, immunotherapy, and combinatory therapeutic strategies." (PMID 29179523, 2017). "A 47-year-old female with recurrent BRAF mutant positive melanoma received combination anti-PD-1 and anti-CTLA-4." (PMID 28239462, 2017). "The combination of BRAFi and MEKi has been approved by the FDA as first‐line treatment for BRAF‐mutant melanoma patients." (PMID 29094484, 2017). "This is the first report presenting CD13/ANPEP and FLI1 as important mediators of resistance to BRAF inhibition with potential as drug targets in BRAFi refractory melanoma." (PMID 29048432, 2017). "The majority of melanomas have an activated MAPK pathway, and recently, melanoma tumors were stratified into genomic subtypes according to mutations in the BRAF, RAS, or NF1 genes." (PMID 28267273, 2017). "Examples of actionable mutations include RAS (KRAS and NRAS), BRAF and PI3 K in colorectal cancer, BRAF or NRAS as well as KIT in malignant melanoma, and others." (PMID 28137276, 2017). "∙ In melanoma patients following treatment with ipilimumab, or after treatment with ipilimumab and a BRAF inhibitor (2014)." (PMID 28404974, 2017). "These tumors were enriched in PTEN mutations, confirming frequent co‐occurrence of BRAF and PTEN mutations in melanoma." (PMID 28267273, 2017). "In this study, we demonstrate that in BRAFV600E melanoma cell lines, activating MEK mutations drive resistance and contribute to suboptimal growth of melanoma cells following the withdrawal of BRAF inhibition." (PMID 28263969, 2017). "Treatment with BRAF/MEK inhibitors is actually a cornerstone in melanoma although in some of them the duration response is limited and the best responders show peculiar clinical features." (PMID 29285320, 2017). "The patient in this study had a BRAF-V600E-mutant melanoma and would be considered to be a strong candidate for vemurafenib (VEM) as first-line therapy, since VEM targets this mutation." (PMID 28537897, 2017). "BRAF positive melanomas were more likely to reveal hyporreflective cells (p = 0.02), epidermal nests (p = 0.02), dermal-epidermal junction nests (p = 0.05), edged papillae (p = 0.05), and bright dots (p = 0.05)." (PMID 28662062, 2017). "Cross-resistance to BRAF-, MEK1/2- and PI3K/mTOR-specific inhibitors in BRAF mutant melanoma cells has been demonstrated." (PMID 29296217, 2017). "Using this method, we recently found that higher expression of HGF, MET, and VEGF-A genes correlates with lower sensitivity to a BRAF(V600E) inhibitor in melanoma cells." (PMID 28453553, 2017). "For instance, Vemurafenib (BRAF inhibitor) elicited only a 5% response rate in BRAF-mutant CRC patients in contrast to dramatic responses seen in BRAF-mutant melanoma patients." (PMID 28640835, 2017).
melanoma (continued). "Targeted therapies with MAPK pathway kinase inhibitors (KIs) have been developed thanks to the discovery that BRAF and NRAS mutations are among the major oncogenic drivers of melanoma proliferation and survival." (PMID 28118616, 2017). "Jiang and coworkers have already presented data showing that BRAF inhibitor resistant melanoma cell lines increase the expression of PD-L1 using the PI3K-STAT3 pathway." (PMID 28978110, 2017). "Growth factors allow BRAF-inhibited melanoma cells to overcome inhibition by activating alternative signalling pathways." (PMID 28708099, 2017). "Current cancer therapies have focused on targeting driver mutations, including oncogenic BRAF and NRAS, which are frequent in melanomas." (PMID 28157711, 2017). "Despite success in pre-clinical testing, only two MEK inhibitors, trametinib and cobimetinib, have been approved, both for treatment of BRAF-mutant melanoma." (PMID 28474232, 2017). "Approaches to prolong responses to BRAF targeting drugs in melanoma patients are challenged by phenotype heterogeneity." (PMID 28606996, 2017). "There are a large number of commercial methods based on polymerase chain reaction (PCR) available for BRAF determination in melanoma." (PMID 28228113, 2017). "In BRAFV600E mutant melanoma, lower levels of BRAFV600E cfDNA were associated with a higher ORR and increased PFS in patients treated with BRAF inhibitors." (PMID 29100459, 2017). "This sets the stage for large‐scale pre‐clinical evaluation of drugs such as BET bromodomain inhibitors as a means of blocking drug adaptation and increasing cell killing by MAPK inhibitors in a subset of BRAF‐mutant melanomas." (PMID 28069687, 2017). "When applied to mutant BRAF melanoma, we found that our approach exhibited significant predictive power." (PMID 28085880, 2017). "Targeting RhoJ signaling with existing PAK inhibitors was more efficient at blocking the progression of BRAF mutant tumors in vivo when compared to kinase inhibitors currently used to treat melanoma." (PMID 28753606, 2017). "In this study, we highlight the ability of HGF to rescue BRAFV600E mutant melanoma cell lines from the effects of BRAF and/or MEK inhibition, observing evidence of HGF rescue in the majority of profiled cell lines." (PMID 28147313, 2017). "Short-term treatment of nascent melanoma tumors with PAK inhibitors that block RhoJ signaling halts the growth of BRAF mutant melanoma tumors in vivo and induces apoptosis in melanoma cells in vitro via a BAD-dependent mechanism." (PMID 28753606, 2017). "The main strategies currently used for treating advanced melanoma include targeted therapies (e.g. BRAF inhibitors, such as vemurafenib) and immunotherapy (e.g. anti-CTLA-4 antibodies, such as ipilimumab)." (PMID 28417283, 2017). "Mutations in BRAF, NRAS, or KIT are present in more than 60% of melanoma cases, but a useful blood-based biomarker for the clinical monitoring of melanoma patients is still lacking." (PMID 28484715, 2017). "Alternate splicing of oncogenic BRAF is the most common driver of acquired resistance to BRAF inhibitors and is evident in approximately 30% of resistant melanomas." (PMID 28503307, 2017). "Nevertheless, similar to what is seen in MITF‐high cells, conditioned medium from BRAF inhibitor pre‐treated melanoma cells profoundly protects AXL‐high cells from the growth inhibitory effect of BRAF inhibition." (PMID 28606996, 2017). "The increase in CD47 expression was mediated by ERK signalling, as it was associated with rebound activation of ERK and co-knockdown of ERK1/2 by siRNA diminished upregulation of CD47 in melanoma cells after exposure to BRAF/MEK inhibitors." (PMID 29050218, 2017). "But, based on the significantly better survival outcomes, the combined BRAF and MEK inhibition will obviously be the mainstay therapy for the BRAF V600-mutant melanoma." (PMID 28416755, 2017).
melanoma (continued). "Intriguingly, CD271 inactivation not only resulted in decreased melanoma cell survival, but also in increased sensitivity to BRAF inhibitor treatment, suggesting that CD271 confers therapy resistance." (PMID 29215016, 2017). "Although it is believed that BRAF mutation and the mitogen-activated protein kinase (MAPK) pathway play critical roles in the pathogenesis of melanoma, how the MAPK signaling is regulated in melanoma carcinogenesis is still not fully understood." (PMID 29187213, 2017). "While the option of targeted therapy is available for patients with BRAF V600‐mutant melanoma, patients with melanomas of the RAS, NF1, or triple‐wild‐type subtypes usually have no efficient therapeutic option besides immunotherapy." (PMID 28267273, 2017). "We found that ATRA enhances the growth of melanoma cells in the presence of the BRAF inhibitor PLX4032." (PMID 29137417, 2017). "Adaptive resistance to targeted therapy such as BRAF inhibitors represents in melanoma a major drawback to this otherwise powerful treatment." (PMID 29299138, 2017). "The observation that RhoJ modulates the expression of complex I components but does not affect tumor angiogenesis in our model identifies RhoJ signaling as a novel regulator of metabolic adaptation in BRAF mutant melanoma cells." (PMID 28753606, 2017). "A. PCR analysis of BRAF cDNA from pre-treatment (Pre) and matching melanomas progressing (Prog) on BRAF inhibitor monotheraphy." (PMID 28503307, 2017). "In recent years, targeted drugs against BRAF have shown remarkable therapeutic success for a subset of patients with advanced malignancies including melanoma, non-small cell lung cancer (NSCLC) and other malignancies, leading to their FDA approval." (PMID 29137342, 2017). "There is evidence for the efficacy of novel systemic agents, both targeted BRAF inhibition and immunotherapy, in brain metastases from melanoma." (PMID 28819707, 2017). "A second patient, a 45-year-old female with a BRAF wild-type melanoma, received anti-PD-1 monotherapy and became thrombocytopenic 43 days later." (PMID 28239462, 2017). "The melanoma-driver mutations in NRAS and BRAF are mutually exclusive but the contribution of RAF signalling downstream of NRAS remains to be clarified." (PMID 28497782, 2017). "Elevated PD-L1 expression was observed in BRAF inhibitor-resistant melanoma cell lines and tumor samples." (PMID 29156850, 2017). "Convincing evidence using preclinical mouse models of melanoma demonstrates that pharmacological targeting of oncogenic pathways such as BRAF and PI3K signaling can increase sensitivity to immune checkpoint blockade." (PMID 28714919, 2017). "Upon depletion of MITF in the pretreated cells, the protective effect on non‐pretreated melanoma toward BRAF inhibitors was abrogated." (PMID 28694322, 2017). "How does lymphocyte infiltration of the melanoma microenvironment decline after the initial increase by treatment with BRAF/MEK inhibitors remains to be fully understood." (PMID 29050218, 2017). "Changes in tumor CD73 expression has been recently seen in BRAF-mutant melanoma patients receiving BRAF/MEK inhibitors and in BRAF-mutant melanoma cell lines." (PMID 29202855, 2017). "Whole-exome sequencing of 20 melanoma patients before and after treatment with BRAF inhibitors identified that four patients with disease progression had BRAFV600E copy-number gain relative to baseline tumours from the same patient." (PMID 28282860, 2017). "Trametinib (MekinistTM Novartis, Mission Viejo, California, USA), a MEK 1/2 inhibitor, has shown therapeutic promise as either a monotherapy for BRAF-mutant melanoma or in combination with dabrafenib." (PMID 29179523, 2017). "Using an shRNA screen selectively targeting genes involved in metabolism in BRAFV600E and BRAF wild‐type melanoma cell lines, HMG‐CoA lyase (HMGCL) was identified as a possible SL partner to BRAFV600E." (PMID 28097822, 2017).
melanoma (continued). "Regardless of the precise mechanisms altering the splicing of BRAF, downstream MEK and ERK inhibition effectively inhibit the proliferation of BRAF inhibitor resistant melanoma cells expressing BRAF splice variants." (PMID 28503307, 2017). "In a recent study of a cohort of 75 tumours from patients with a mucosal melanoma, NF1 and RAS mutations were identified in 18.3 and 16.9% samples, respectively, whereas 8.4 and 7% of tumour samples harboured BRAF and KIT mutations." (PMID 28637487, 2017). "New primary cutaneous malignancies, including cutaneous squamous cell carcinoma (cuSCC), basal cell carcinoma, keratoacanthoma and melanoma have been reported in patients receiving BRAF inhibitor, most of which are cuSCC." (PMID 29137342, 2017). "We predicted 842 combinations to be synergistic, 890 to be effective, and 304 to be both effective and synergistic in context of mutant BRAF melanoma." (PMID 28085880, 2017). "Synergistic activity was seen with TAK-733 in combination with the pan-RAF inhibitor TAK-632 in both BRAF-mutated melanoma cells and NRAS-mutated melanoma cells with acquired resistance to BRAF inhibitors." (PMID 27650277, 2017). "In this study we used photoacoustic imaging (PAI) and magnetic resonance imaging (MRI) to assess the PD biomarkers of the downstream cellular changes that follow the inhibition of Hsp90 and BRAF signaling in melanoma cells." (PMID 28811486, 2017). "Paradoxically, treatment of melanoma cells or fresh melanoma isolates with BRAF/MEK inhibitors resulted in upregulation of CD47." (PMID 29050218, 2017). "Given its principal role in melanoma initiation and progression, oncogenic BRAF has become a druggable kinase and a crucial target for small-molecule inhibitors." (PMID 28158294, 2017). "Recently, it has been shown that integrin β1-mediated matrix adhesion and signaling can drive melanoma resistance to BRAF inhibition." (PMID 28188308, 2017). "In a previous PDOX study of a BRAF-V600E-mutant melanoma, TRA, an MEK inhibitor, was the only agent of the 4 tested that caused tumor regression." (PMID 28537897, 2017). "Results were similar in BRAF mutated (A375, HT144 and 451Lu), NRAS mutated (WM852c), and patient melanoma cells (MB2309 and MB2141)." (PMID 27086916, 2017). "In conclusion, our data strongly support the idea that BAG3 can represent a valid target in the treatment of BRAF inhibitor resistant metastatic melanomas." (PMID 29113311, 2017). "In melanoma, BRAF (71%) followed by CDKN2A (21%) were reported with the highest number of mutations." (PMID 28371134, 2017). "The corresponding decrease in glycolytic activity can be visualized by PET-CT scanning in melanoma patients treated with BRAF inhibitors, showing a reduced uptake of glucose in the tumor tissue." (PMID 29137417, 2017). "The investigators examined the heterogeneity of the melanoma phenotypes upon treatment with a BRAF inhibitor, using MITF as readout." (PMID 28694322, 2017). "Inhibition of mutant BRAF by specific kinase inhibitors has proven a successful strategy in the treatment of malignant melanoma." (PMID 29050239, 2017). "ATP‐competitive inhibitors such as vemurafenib provide significant clinical benefit in treating BRAF‐mutant melanoma." (PMID 29175850, 2017). "To further elucidate the role of Usp9x in melanoma and examine the sensitivity of NRAS mutant tumours to Usp9x KD and inhibition, we first assessed the effects of Usp9x KD on specific RAS proteins in highly metastatic NRAS and BRAF mutant melanomas." (PMID 28198367, 2017). "In the blood sample of melanoma patients, vemurafenib, a BRAF inhibitor, decreased the frequency of monocytic myeloid-derived suppressor cells (MDSCs)." (PMID 29156850, 2017). "This increase was also seen at mRNA level in A375‐T cultures as well as in a whole range of BRAF inhibitor‐treated melanoma cells including ex vivo cultures." (PMID 28606996, 2017).